INS (insulin)
Diseases named in the same sentence as INS in open-access papers (continued):
Sharing a sentence is not in itself a finding about the gene and the disease.
diabetes (continued). "People with diabetes (typically type 2) have low blood glucose levels because their bodies do not use insulin properly and their blood sugar levels are higher compared to people without diabetes." (PMID 35795845, 2022). "We speculated that the elevated Cer with saturated FA may be more relevant with high insulin levels and HOMA-IR, exacerbating the development from PreDM to diabetes as compared with other types of Cer." (PMID 36060983, 2022). "Both insulin- as well as nNOS-containing endocrine cells were almost absent 24 h after the onset of diabetes." (PMID 35563364, 2022). "This notion is consistent with cohort studies showing elevated insulin levels and diabetes as predictors for the incidence of AD in APOEε4 negative individuals." (PMID 36555450, 2022). "Diabetes mellitus (DM) characterized by hyperglycemia is a chronic, complex metabolic syndrome resulting from either lack of insulin release, insulin resistance or both." (PMID 36388939, 2022). "The analysed outcomes included gastrointestinal markers and various intermediate markers of diabetes and CVD, including blood glucose and insulin concentrations, blood lipids, and markers of atherosclerosis (i.e., aortic fatty streak and advanced lesions in carotid arteries)." (PMID 34075432, 2022). "Another study looked at patients with COVID-19 and diabetes comparing the laboratory values between those who took insulin supplementation in comparison to those who did not." (PMID 36051728, 2022). "This study is limited by the self-reported nature of a diabetes diagnosis and the lack of information on the classification and severity of diabetes (type I vs. type II, insulin requiring or non-insulin requiring)." (PMID 36777658, 2022). "Depending on the person with diabetes, basal insulin or premixed insulin (with or without oral antidiabetic drugs) can be used to initiate insulin therapy." (PMID 36330105, 2022). "These patients also had increased utilization of insulin (27.0%), insulin secretagogues (29.9%), and DPP4i (22.3%) compared to those with diabetes without CVD/HF." (PMID 35606699, 2022). "Diabetes mellitus (DM), a mixture of heterogeneous problems, is usually characterized by hyperglycemia and glucose bigotry scenes resulting from the lack of insulin production, insulin resistance, or both." (PMID 35434401, 2022). "Type 1 diabetes mellitus (T1D) is a mostly immune-mediated disease characterised by the destruction of pancreatic β-cells, which results in an almost complete lack of insulin in the body." (PMID 35740440, 2022). "In this study, 252(62.7%) of the respondents were T2 DM, 140(34.8%) had a family history of diabetes, 204(50.7%) were on insulin injection, and 214(53.2%) did not receive diabetic education." (PMID 35797276, 2022). "In HNC, 2 patients had diabetes (Type II- no insulin), 1 had oesophageal reflux disease, 1 had gastrointestinal disease (oesophagitis) while 4 patients had been previously treated for cancers (2 for prostate and 1 each for uterus and skin)." (PMID 36558884, 2022). "It is also essential to differentiate insulin overdose from sepsis or infections of various origins, especially those without diabetes." (PMID 35324747, 2022). "Autoantibody positivity is inversely correlated with diabetes duration but does not appear to strongly correlate with C-peptide, a by-product of insulin synthesis and a biomarker for exogenous insulin requirement." (PMID 36181724, 2022). "Recently, continuous glucose monitoring (CGM) systems, with and without insulin pump therapy, have revolutionized diabetes care." (PMID 36422278, 2022). "In diabetes, an elevation in polyol pathways takes place in tissues where insulin is not mandatory for cellular glucose uptake, such as the retina, kidney and peripheral nerves." (PMID 35164215, 2022).
diabetes (continued). "In comparison with their insulin-sensitive peers, young healthy insulin-resistant individuals without diabetes manifest alterations throughout the α-dicarbonyls-AGEs-sRAGE axis, dominated by higher 3-deoxyglucosone levels." (PMID 36432614, 2022). "Women with gestational diabetes mellitus in whom glucose tolerance becomes normal postpartum remain insulin-resistant compared to women with no history of this type of diabetes." (PMID 35330341, 2022). "As a result of the OpenAPS Data Commons, it is now possible to assess research questions and expand the knowledge of insulin-requiring diabetes in ways that were not possible before due to a lack of truly large-scale diabetes data." (PMID 35565875, 2022). "In the current model, deletion of OGA in β-cells led to glucose intolerance and insulin secretion deficits in older mice, though animals did not develop hyperglycemia or overt diabetes." (PMID 36387851, 2022). "miR-143 modifies insulin-mediated Akt activation and glucose homeostasis by downregulating the oxysterol-binding-protein-related protein 8 (ORP 8); therefore, the miR-143-ORP8 pathway acts as a critical therapeutic target for obesity-induced diabetes." (PMID 36613495, 2022). "In people suffering from diabetes mellitus, the quantity of secreted insulin is never enough in order to induce sufficient glucose absorption, leading to the continuous circulation of glucose in the blood stream." (PMID 35736019, 2022). "Here, we hypothesized that the likely pathogenic heterozygous variant in WFS1 might possibly explain the patient's early-onset diabetes and the efficacy of GLP1-RA on prandial insulin interruption." (PMID 35227307, 2022). "Diabetes Mellitus is a disorder in which glucose is not oxidized to produce energy due to a lack of insulin." (PMID 35846869, 2022). "These drugs are commonly used to treat diabetes, and they mimic the action of an incretin hormone called GLP-1, which is released from the L cells of the small intestine after meals to stimulate insulin secretion, reduce glucagon production, and retard gastric emptying." (PMID 36148775, 2022). "Diabetes mellitus (DM), a metabolic disorder characterized by chronic hyperglycemia, derives from either a lack of or resistance to insulin." (PMID 36551765, 2022). "Maturity-onset diabetes of the young (MODY; MIM#606391) is a non-autoimmune monogenic form of diabetes mellitus with characteristic destruction of pancreatic β cells and impaired insulin biosynthesis." (PMID 35246208, 2022). "An intravenous insulin infusion in people without diabetes provoked a decline in the leucine flux due to a reduction in protein breakdown, without an effect on protein synthesis." (PMID 35931683, 2022). "Here we report using a mouse model of diabetes presenting with hyperglycemia (but with no change to insulin levels), that both mitochondrial structural and functional remodelling occurs." (PMID 35046471, 2022). "Although we observed higher diabetes incidence with spermidine treatment, spermidine did not worsen insulitis in diabetic mice and did not alter pancreatic insulin content and the insulin granule pool in nondiabetic mice." (PMID 35296698, 2022). "A lack of physiological action of insulin in diabetes mellitus (DM) induces an impaired metabolism of carbohydrates, lipids, and proteins, which are the necessary components for cellular homeostasis and tissue activities." (PMID 36233586, 2022). "The PRS also helps elucidate aetiologically different diabetes subgroups at diagnosis, in the absence of insulin secretion/resistance measures, and these differ in their association with future complications." (PMID 35587468, 2022). "Latent autoimmune diabetes in adults (LADA) is a type of diabetes characterized by slow autoimmune damage of pancreatic β cells without insulin treatment in the early clinical stage." (PMID 35937817, 2022).
diabetes (continued). "Diabetes mellitus (DM) is a metabolic disorder that is characterized by hyperglycemia resulting from insulin deprivation (Type I) or lack of cell response to insulin (Type II)." (PMID 36676988, 2022). "Laboratory tests and questionnaires of the National Health and Nutrition Examination Survey 2009–2016 classified 774 participants reporting taking insulin, 2758 participants reporting T2D not taking insulin, and 17,796 participants without diabetes." (PMID 36014790, 2022). "In a study of more than 400,000 patients with cancer in Denmark, all patients with diabetes who were treated with oral hypoglycemic agents or insulin had a higher mortality rate than those without diabetes." (PMID 35887596, 2022). "There were significantly increase of the levels of BMI, waist circumference, systolic blood pressure, total cholesterol, TG, FBG, 2 hours postprandial blood glucose (2hPBG), insulin, and HOMA-IR in the diabetes and prediabetes groups than in the control group (P < .05 or P < .01)." (PMID 36253996, 2022). "Similar to the liver, treatment of the STZ mice with insulin or vitamin D did not affect the repressive effect of the STZ-induced diabetes on the Cyp2r1 expression in the kidney." (PMID 35524739, 2022). "The next evolution in diabetes technology was the shift toward closed-loop systems, where the pump and CGM data are processed through an algorithm (on the pump or on a separate mobile device) and adjustments to insulin dosing are auomatically enacted." (PMID 35565875, 2022). "In addition, a molecular analysis revealed that phycocyanin protects against diabetes mellitus by activating the AKT and AMPK signaling pathway in both the high glucose high fat diet induced mouse and insulin-resistant SMMC-7721 cell models." (PMID 37430932, 2022). "For patients with diabetes, the same parenteral nutrition formulae as for patients without diabetes can be used, as long as blood glucose levels can be adequately controlled using insulin." (PMID 36992742, 2022). "From 1988-1994 to 2013-2020, there was no significant change in the percentage of adults using insulin or the prevalence of glycemic control and severe hyperglycemia among US adults with diabetes using insulin." (PMID 36538330, 2022). "Diabetes mellitus (DM) is a chronic disturbance that occurs when the hypoglycemic hormone insulin is not released in adequate amounts or when its activity is ineffective due to metabolic resistance." (PMID 35631785, 2022). "Diabetes mellitus is a disease that occurs when the pancreatic beta cells do not secrete insulin, or the systemic cells are resistant to insulin." (PMID 35300109, 2022). "Due to the high cost of insulin, it is difficult for people with diabetes without insurance or with private high-deductible insurance plans to pay for insulin." (PMID 35436214, 2022). "Illustrative quotations are given with participant research number, T2DM or prediabetes status, and diabetes medication (insulin or class of oral medication) used or not used." (PMID 36221145, 2022). "Lack of knowledge on diabetes and insulin among diabetes patients was reported as a barrier to insulin prescription in different studies." (PMID 36554673, 2022). "Our study suggests that beta cell impairment represented by insulin treatment in GDM pregnancy seemed to increase the CVMM risk, irrespective of subsequent diabetes prior to CVMM." (PMID 36085031, 2022). "We have developed a simple and easy perioperative hypoglycemia risk prediction model among T2DM patients undergoing elective surgery, which contains four predictors: duration of diabetes, BMI, SDBG, and subcutaneous injection of insulin as a preoperative hypoglycemic regimen." (PMID 35538461, 2022). "The overall percentage of adults with diabetes who used insulin did not change significantly, from 30.5% in 1988-1994 to 28.2% in 2013-2020 (P = .81 for trend) (eTable 1 in Supplement 1)." (PMID 36538330, 2022).
diabetes (continued). "In the pathogenesis of diabetes, inflammatory factors, such as interleukin (IL)-1β, IL-8, tumor necrosis factor (TNF)-α, and induced nitric oxide synthase (iNOS), are important factors related to insulin sensitivity." (PMID 35056765, 2022). "Protein, grains, and vegetables contributed more to the group reporting taking insulin’s daily total energy intake compared to participants without diabetes, whereas beverage and alcohol contributed less." (PMID 36014790, 2022). "In AID, a control algorithm automatically adjusts the insulin delivery of an insulin pump in response to readings from a continuous glucose monitor (CGM) to help improve glycemic levels and variability and reduce the day-to-day burden in diabetes management." (PMID 35834298, 2022). "Taken together, the experimental findings revealed that insulin injection could reduce blood glucose levels and correct the insulin resistance levels in patients with AIS diabetes mellitus." (PMID 36060656, 2022). "It is known that serum UA levels co-vary with insulin levels, insulin resistance, and pre-diabetes in people without SCI." (PMID 36278750, 2022). "Type 2 diabetes mellitus (T2DM) is the main category of diabetes in adults, which is characterized by steady deterioration of glycemic control due to progressive β-cell dysfunction of insulin secretion frequently on the background of insulin resistance." (PMID 35045841, 2022). "A study of Japanese Americans found that greater visceral adiposity preceded the development of T2DM and also demonstrated an effect independent of fasting insulin, insulin secretion, glycemia, total and regional adiposity, and family history of diabetes." (PMID 35495951, 2022). "Hyperglycemia, which is brought about by an absence of insulin discharge as insulin advancement, is an indication of diabetes." (PMID 35268815, 2022). "Information regarding treatment was available for 409 (98.7%) of the 414 women with pregestational diabetes: 60.6% reported using oral medications; 10.0%, insulin; 15.4%, both treatments; 5.6%, diet only; and 8.3%, no treatment." (PMID 36419098, 2022). "But when beta cells are faulty and do not generate sufficient insulin levels, or when insulin lacks the ability to stimulate cells to take up glucose, diabetes can develop." (PMID 35188462, 2022). "Besides the effects of ATM-sEVs on insulin function, studies have shown that bone marrow-derived M-sEVs (BMM-sEVs) also play a role in the development of diabetes." (PMID 35832790, 2022). "Insulin transport by capillary endothelial cells in the BBB is affected by many systemic factors, including those related to metabolic disorders, i.e., obesity, systemic inflammation, or diabetes." (PMID 35563135, 2022). "It is not surprising that the pancreas and insulin production remain a dominant thought on the minds of diabetes patients." (PMID 36141360, 2022). "Diabetes mellitus (DM) is a multifactorial disease characterized by a hyperglycemic chronic state that results from resistance to or lack of insulin secretion from the pancreas." (PMID 36501263, 2022). "Although IBCs derived from 125Tg.NOD bind insulin with a high affinity of 3 × 10-8 M, these mice develop diabetes similarly to non-transgenic NOD counterparts." (PMID 36275764, 2022). "The diabetes models with downregulated S6K, Akt1, and chico were complementary to the HSD model in pharmacological research and indicated the effect position of a certainly tested compound on the whole insulin-related pathway." (PMID 36035393, 2022). "In particular, in type 2 diabetes mellitus, the body cells do not use insulin effectively, and consequently, the glucose level goes up." (PMID 36544524, 2022). "Numerous studies have shown significant clinical benefits of using CGM in patients with diabetes, regardless of insulin administration." (PMID 36514151, 2022). "Online crowdfunding has not been well studied in people with diabetes despite its prevalence and the high cost of insulin." (PMID 35436214, 2022).
diabetes (continued). "Although mutations in the KLF11 gene have been linked to maturity onset diabetes of the young type VII, KLF11 KO mice have decreased circulating insulin levels and increased insulin sensitivity, but do not develop overt diabetes." (PMID 35413089, 2022). "In another trial, depending on the adherence rate, 70–90% of patients with diabetes who initially presented on insulin and followed a low-calorie diet with carbohydrate restrictions were no longer taking insulin after one year." (PMID 36079756, 2022). "It was found that the levels of several clinical characteristics related to diabetes including age, BMI, HOMA-IR, Insulin, FPG, OGTT-0.5h PG, OGTT-1h PG, OGTT-2h PG, OGTT-3h PG and HbA1c were significantly increased in both PreDM and T2DM groups as compared with those in NC group." (PMID 36060983, 2022). "The included publications were not research specifically focussing on diabetes management with insulin for people with intellectual disabilities, so a more in‐depth study to address this is required." (PMID 35983585, 2022). "Diabetes mellitus is a chronic metabolic disorder in which the pancreas secretes insulin but the body cells do not recognize it." (PMID 36296403, 2022). "The key feature of non-obese T2D seems to be a defect in the insulin secretion capacity as opposed to peripheral insulin resistance described in classical diabetes." (PMID 36614099, 2022). "NAFL: nonalcoholic fatty liver; NAFLD: nonalcoholic fatty liver disease; ALT: alanine aminotransferase; GGT: gamma-glutamyl transpeptidase; TGs: triglycerides; AST: aspartate aminotransferase; DM: diabetes mellitus; NASH: nonalcoholic steatohepatitis; HAIR: hypertension, ALT, insulin resistance." (PMID 35518541, 2022). "Moreover, licorice flavonoid oil exhibited therapeutic effects against diabetes and hyperglycemia in the KK-Ay mice by regulating glucose metabolism through AMPK pathway and the insulin levels in skeletal muscle." (PMID 35082907, 2022). "The negative emotional response of patients towards receiving insulin therapy through the course of diabetes is referred as insulin distress, which is not only a part of diabetes distress, but it is unique identity." (PMID 35681150, 2022). "The top preconception feature variables impacting the model outputs were HbA1c, fatty liver index, mean arterial blood pressure, fasting insulin, TG/HDL ratio, height, age, mid-upper arm circumference, BMI, parity, alcohol consumption, family history of diabetes mellitus and Chinese ethnicity." (PMID 35682375, 2022). "Regular soft drinks did not rank in the top 10 most energy contributing food subcategories list among the group reporting taking insulin, but was ranked 5th among those with T2D but not taking insulin, and 2nd among participants without diabetes." (PMID 36014790, 2022). "Diabetes mellitus is a group of non-communicable metabolic diseases characterized by prolonged hyperglycemia resulting from defects in insulin secretion, insulin action, or both." (PMID 35214168, 2022). "The search algorithm for PubMed was as follows: (“glycyrrhizic acid” OR “glycyrrhetinic acid” OR “ammonium glycyrrhizinate” OR “diammonium glycyrrhizinate” OR “dipotassium glycyrrhizinate”) AND (“diabetes” OR “insulin” OR “lipid”) with no other restrictions." (PMID 36232291, 2022). "We showed this improved insulin sensitivity even if the participants with overfat constitution were without diabetes and within the normal range of HbA1c." (PMID 35677551, 2022). "In terms of the treatment modality of diabetes, the aOR (95% CI) was lowest in the oral hypoglycemic agent group (1.47 (1.08–2.01)) and highest in the insulin group (6.63 (3.04–14.44)) compared to the no diabetes group." (PMID 35079073, 2022). "Ketosis-prone type 2 diabetes is a form of diabetes that usually presents with diabetic ketoacidosis (DKA) in patients who are not insulin dependent." (PMID 36348924, 2022).